MUC1 (mucin 1, cell surface associated)
Diseases named in the same sentence as MUC1 in open-access papers (continued):
Sharing a sentence is not in itself a finding about the gene and the disease.
tumor (continued). "One of the many effects of the signal transduction produced by the MUC1/Y protein is the enhancement of tumour progression." (PMID 34452200, 2021). "We demonstrated that the newly developed, fully human CIM301-1 and CIM301-8 antibodies also functionally bind to MUC1-Tn/STn epitopes on tumor cell lines, and are capable of enhancing NK cell-mediated cytotoxicity upon binding to CD16." (PMID 34070311, 2021). "In the proliferation analysis, down-regulation of MUC1 in HCCC9810 cells resulted in a significant inhibition of tumor cell proliferation potential (P < 0.001)." (PMID 34729096, 2021). "NK cell-mediated responses against MUC1+ Jurkat tumor cells were importantly enhanced by the antibody, but antibody concentrations higher than 1 μg/mL showed no additional beneficial effects." (PMID 34070311, 2021). "The tumor compartment, identified as Cluster-7 is characterized by high expression of EpCAM, MUC1, E-Cadherin and CA125, and low expression of pan-leucocyte marker CD45." (PMID 33135052, 2021). "They showed that overexpression of MUC1 in over 80% of PDA patients and its aberrant expression increases the levels of NRP-1 and VEGF, which subsequently causes a pro-angiogenic tumor microenvironment." (PMID 33836774, 2021). "For instance, COL8A1, COL8A2, and COL21A1 were only detected in normal tissues whereas COL7A1 and MUC1 were exclusively identified in tumor samples." (PMID 34199725, 2021). "The second is MUC1 expressed by cancer cells can affect the phenotype and function of immune cells in the tumor microenvironment." (PMID 34207342, 2021). "In fact, not only tumors grew at a significantly faster rate in MUC1KO mice, but the tumor weights were significantly higher in MUC1 KO mice compared to the WT mice." (PMID 34070449, 2021). "The construction of MUC1 glycopeptide vaccines by presenting α-GalCer adjuvants and antigens on gold NPs has also been proposed; this technique can potentially enhance anti-tumor responses during cancer immunotherapy." (PMID 34207342, 2021). "Other studies revealed the promising use of cancer immunotherapy involving a monoclonal antibody (5E5) that targets the aberrant Tn glycoform of MUC1 and is able to kill the tumor cell." (PMID 34638920, 2021). "Interaction of TF on mucin protein MUC1 on tumor cells with galectin-3 increases tumor cell–cell homotypic aggregation and promotes tumor cell emboli formation and survival in the circulation." (PMID 34944925, 2021). "A different sensitivity in the response to cytotoxic agents has already been reported for MUC-1 and H295R cells, with MUC-1 showing to be more chemoresistant than the primary tumor cells due to their metastatic origin." (PMID 34834449, 2021). "It is said that cytoplasmic tail of the mucin is identical in normal and tumour cells and the greatest difference between normal and malignant cells is in MUC1 localization." (PMID 34681197, 2021). "We have shown previously that MUC1 expression in the tumor helps in maintaining the MDSCs in an immature and immunosuppressive state, leading to an aggressive nature of MUC1+ PDA tumors." (PMID 34070449, 2021). "MUC1 can affect E-cadherin and β-catenin expression and interact with E-selectin, making tumor cells easily adhere to vascular endothelial cells and cross vascular walls, to facilitate the metastasis of tumor cells." (PMID 34976785, 2021). "The detection of the circulating MCF-7 tumor cells was possible because of the selective recognition of the MUC-1 over-expressed on the MCF-7 cell by an MUC-1 aptamer." (PMID 33494499, 2021). "In this study, we combined EpCAM/CD3 BsAb and MUC-1/CD3 BsAb to target both EpCAM and MUC-1 on the surface of tumor cells." (PMID 34522164, 2021). "Herein, we describe the generation of fully humanized antibodies based on the murine 5E5 antibody, targeting the tumor-specific MUC1-Tn/STn epitope." (PMID 34070311, 2021). "We would therefore expect lower levels of MUC1 in older women, if they have less aggressive tumours." (PMID 34165702, 2021).
tumor (continued). "The results showed that in 90% (27/30) of all pairs, the MUC1 mRNA expression was significantly up-regulated in ICC tissues compared to adjacent non-tumor liver tissues (P = 0.039)." (PMID 34729096, 2021). "Sufficient quality of immunohistochemical staining of MUC1 expression was achieved in 158 of 165 tumor samples (gem: n = 88, obs: n = 70)." (PMID 34386419, 2021). "Increasing numbers of tumour cells were implanted into the mammary fat pad of mice and 0.5 × 105 C75mg.MUC1 and 1 × 105 C57mg.WT cells were determined as the optimal cell number for tumour inoculation." (PMID 34066318, 2021). "While the VLP vaccine delivering both antigens induced a significant survival benefit in wild-type mice, it was unable to suppress tumour growth in MUC1.Tg mice." (PMID 34066318, 2021). "The expression of MUC1 promotes angiogenesis in cancer and, to a certain extent, promotes tumor migration and invasion." (PMID 34207342, 2021). "In contrast to the majority of the adrenal patient-derived xenograft, MUC-1 xenografts showed the engraftment of large solid tumors, marked tumor growth, and the maintenance of pathological and endocrine features." (PMID 34567112, 2021). "MUC1 induces angiogenesis in tumor microenvironments by increasing the expression of neuropilin-1 (NRP1, a co-receptor of VEGF) and its ligand VEGF." (PMID 34207342, 2021). "In our paper, we also demonstrated that both the primary tumor H295R cell line and the metastatic MUC-1 cells produce CXCL12 and express its receptors." (PMID 34834449, 2021). "The target antigens for gene-modified DC vaccines can be provided from the data of single-cell RNA-sequencing and previous well-known pro-tumoral tumor antigens, e.g., MUC1." (PMID 33692796, 2021). "MUC1 differs between tumor and normal cells, the former characterized by aberrant, truncated glycosylation, yielding glycopeptide epitopes that can be recognized by specific antibodies." (PMID 33084221, 2020). "Results showed a reduction of tumors growth in the mice treated with sh-MUC1 compared with that with sh-NC, and there was a reduction of tumor growth in mice treated with miR-497 agomir compared with those treated with agomir-NC (p < 0.05)." (PMID 33194611, 2020). "The results of this in vivo study showed that the MUC1-directed CAR T cells resulted in significantly reduced tumour size which persisted throughout the study length." (PMID 32645977, 2020). "MUC1 is a tumor-related glycoprotein decorated with the TF antigen, and it has been proposed that the aberrant interaction between MUC1 presenting TF disaccharide epitopes, and hGal-3 promotes cancer progression." (PMID 32850631, 2020). "This phenomenon is most likely related to the shedding of MUC1 from the tumor cells and the formation of macromolecular MUC1-[89Zr]Zr-DFO-AR20.5 immune complexes that can persist in the blood and subsequently accumulate in the liver and spleen." (PMID 32429033, 2020). "Although MUC1 is expressed in solid tumors, it is cleaved and shed from the cell surface as the tumor stage progresses, which limits the effectiveness of anti-MUC1 CAR-T cells." (PMID 32560392, 2020). "A strategy with Diphtheria toxin A (DTA) against pancreatic cancer has also been developed, using the tumor-specific promoter MUC1, due to its over-expression in pancreas ductal adenocarcinoma (PDA) and its association with tumor aggressiveness." (PMID 33381459, 2020). "As a transmembrane protein with tumorigenic activities, MUC1 plays an important role in the survival, proliferation, and migration of tumor cells." (PMID 33375426, 2020). "Another preclinical study carried out in the MUC1.Tg mice examined the possibility of immunization of the tumor host with mAb-AR20.5 a tumor antigen-targeting antibody (here: anti-mucin 1, MUC1)." (PMID 32370075, 2020). "This vaccine was able to generate a therapeutic response due to specific immunity against MUC1 and to a non‐specific anti‐tumor response elicited by the adjuvant." (PMID 32594569, 2020).
tumor (continued). "The therapeutic mechanism of AR20.5 is predicated on the antibody forming immune complexes with circulating MUC1 or MUC1-expressing tumor cells and subsequently inducing an immune response to the tumor itself." (PMID 32429033, 2020). "Mucin-1 (MUC-1) is an overexpressed cell surface glycoprotein that is present in the tumor cells of CRC and is confirmed as a biomarker for its early diagnosis." (PMID 32295170, 2020). "Reductions in tumor sizes or tumor marker levels or disappearance of malignant pleural effusion were seen in seven of nine MUC1-positive cancers." (PMID 33679709, 2020). "Among the human ligands, the highly sialylated mucin-1 (MUC-1), which binds Siglec-9, attenuates anti-tumor immunity in tumor-associated macrophages (TAMs)." (PMID 32575400, 2020). "CD28 anti-MUC-1 CAR exploiting the variable fragments of another tumor-specific antibody (TAB004) was used in a preclinical study published in Cells in 2019." (PMID 35582441, 2020). "In combination with the previous finding that down-regulation of MUC1 would inhibit drug resistance in tumor cells, our data indicated that the level of MUC1 was critical in determining the efficiency of anti-tumor drugs targeting PI3K/Akt/mTOR signaling axis." (PMID 33375426, 2020). "Repeat expansions in the transmembrane glycoprotein Muc1 improve tumor cell adhesion to lung tissue and thereby contributes to metastasis." (PMID 32277013, 2020). "In PC cells, it has been reported that the altered O-glycosylation on MUC1 was observed during tumor development and progression, including premalignant lesions under inflammatory conditions, but that study did not analyze it using ABA or ACA." (PMID 32878320, 2020). "Radiation has been shown to increase recognition by and subsequent activation of antigen-specific CD8+ T cells for H522 cell for Brachyury, carcinoembryonic antigen (CEA), and MUC1 tumor antigens." (PMID 32272797, 2020). "Evidence shows that the overexpression of MUC1 is related to cell adhesion inhibition and the increased metastatic potential of tumor cells, especially in breast cancer." (PMID 32194541, 2020). "This complex can be internalized by dendritic cells which facilitates effective antigen-processing and cross-presentation of MUC1 to T cells, and leads to the activation of cytotoxic T cells to kill the tumor." (PMID 33167508, 2020). "The efficacy of anti‐MUC1 ADCs was evaluated using various cancer cell lines and a mouse tumor xenograft model." (PMID 33084221, 2020). "These tumours overexpressing MUC1 generally had high histological grades and high Ki-67 and cyclin D expression and were frequently involved in lymph node metastasis." (PMID 32377198, 2020). "Early studies using mannan conjugated to a peptide of the MUC1 tumor protein described strong type 1 and 2 immune responses and protection against MUC1-expressing tumors in mice, and humans." (PMID 33329540, 2020). "Scoring of macrophages in different geographical regions by manual and automated (using Visiopharm software) methodologies revealed a significant association between MUC1-ST and CD163 on the edge of the tumour nests." (PMID 33149188, 2020). "Within this context, especially mucin-type O-glycan sTn poses a suitable pan-carcinoma glycotarget, given its high, tumor-specific expression on oncoprotein CD44 as well as MUC1, MUC2, MUC5AC, and MUC6." (PMID 33371487, 2020). "This rank was based on the tumour-specific aberrant glycosylation pattern of MUC1 in various forms of adenocarcinoma." (PMID 32377198, 2020). "Promoters for established tumor markers such as α-fetoprotein (AFP) or mucin-1 (MUC1) have been used for this purpose." (PMID 33202717, 2020). "Recent results have also shown that MDSC level correlates with reduction in the adaptive immune response to tumor antigens, e.g., MUC-1, both by lowering the production of specific antibodies and activation of tumor-specific T cells." (PMID 32849517, 2020).
tumor (continued). "When analyzing their plasma samples, we focused on MUC1+ EVs that are known to originate from tumor cells in various malignancies, suggesting that they are TMPs." (PMID 33050539, 2020). "The MUC1 aptamer has also been used for tumor-targeted gene delivery in order to overcome the tunable nonspecific binding of pDNA/PEI complexes (widely used in the field of gene delivery) to negatively charged proteoglycans on cell membranes." (PMID 32842557, 2020). "Tumor regression was observed in the mice following administration of the fusion vaccine against MUC1-positive tumor cells." (PMID 32150821, 2020). "MUC1 can induce the growth of tumour cells through recruiting β-catenin binding to its C-terminal domain." (PMID 32322597, 2020). "Subsequently, DCs were loaded with MUC1 peptides or tumor lysate obtained from malignant pleural effusion specimens of the patients." (PMID 33679709, 2020). "Concurrent inhibition of IGF1R and CDK4/6 has shown a greater decrease in cell viability than achieved by a single drug in both NCI-H295R and MUC1 cells, as reported in different tumor cell lines." (PMID 32373071, 2020). "In vivo studies, on the other side, showed more rapid tumor growth and stronger resistance to disulfiram treatment in CIPp-MUC1 xenograft mice than in wild-type control." (PMID 33375426, 2020). "MUC1 expression was more frequently found in tumors with higher tumor stage and tumor grade of mismatched repair-proficient CRC." (PMID 32168759, 2020). "Nanovaccine with tumor antigen MUC1 mRNA designed against triple negative breast cancer in combination with an anti-CTLA-4 monoclonal antibody can be successfully delivered to DCs in lymph nodes resulting in an enhanced T cell anti-tumor immune response." (PMID 32792853, 2020). "MUC1 is a potential tumor promoter gene and plays an important role in regulating cell invasion, proliferation, survival, and apoptosis." (PMID 32662743, 2020). "Overexpression of MUC1 promoted the growth of ClPp cells in xenografted mice and attenuated the anti-tumor activity of disulfiram in vivo." (PMID 33375426, 2020). "Different therapy approaches targeting primary tumor-initiating cells, including MUC1 and MESO CAR-T cells, are under clinical trials." (PMID 33207601, 2020). "The microenviromental anti-inflammatory properties of bromelain by uncoating cancer cells (depolymerizing MUC-1,fibrin and albumin) is thought to enhance tumor exposure to the host defense by increasing lymphocyte-to-tumor adhesion." (PMID 34466585, 2020). "Several studies have reported that evaluating MUC1 in tumor cells is relating to the evasion of immune recognition and destruction in NSCLC." (PMID 32807223, 2020). "Other tumor markers strongly expressed by the primary culture and individual clones were the mucins MUC1 and MUC16, particularly MUC1 according to RNA sequencing results." (PMID 32293552, 2020). "Muc1 is a multifaceted tumor protein, and its relationship with the kidney has recently been highlighted and has been identified as a mutant that causes mendelian disorder medullary cystic kidney disease type 1." (PMID 32545899, 2020). "Second-generation 4-1BB CAR-T cells exploiting the domains of the 5E5 antibody, which specifically recognizes the aberrantly glycosylated MUC-1, were used to treat disseminated tumor xenografts of intraperitoneally injected Hs766T pancreatic cells." (PMID 35582441, 2020). "Modified MUC1, due to the overexpression of C2GnT, results in immune evasion of tumor cells by NK cells that further results in a longer half-life of tumor cells in circulation." (PMID 32075174, 2020). "A study using a xenograft model with the MiaPaCa2 cell line demonstrated how anti-MUC-1 CAR-T cells were able to reduce tumor weight and metastasis." (PMID 35582441, 2020).
tumor (continued). "Overall, these results demonstrated that the in vivo anti-tumor activity of disulfiram is inhibited by overexpression of MUC1." (PMID 33375426, 2020). "MUC1 is a prototypical mucin, which has been found to be over-expressed on a wide range of tumor cells." (PMID 32351942, 2020). "Conversely, in EL4 tumor model, the MUC1-β-catenin pathway is critical for MDSC development, suggesting a key role in MDSC-mediated immune suppression instead of tumor progression." (PMID 32132993, 2020). "Recently, MUC1‐based glycosylated tricomponent antitumour vaccines demonstrated a clear reduction in tumour burden by eliciting both cellular and humoral immune reactions." (PMID 32745356, 2020). "Strikingly, a similar, high-EMMPRIN expression was also found on blood MV from patients with metastatic breast cancer where it was co-expressed with the tumor marker Mucin-1 (MUC1/CA 15-3)." (PMID 32731639, 2020). "To date, various MUC1-targeting tumor vaccines including peptide/protein vaccines, glycopeptides vaccines, DNA vaccines, and dendritic cell (DC) vaccines have been developed." (PMID 32823603, 2020). "Except for targeting down‐regulated mucins, the mucin gene promoter also will induce tumour cell death in MUC1‐expressing PC." (PMID 32745356, 2020). "The PET images reveal that [89Zr]Zr-DFO-AR20.5 clearly delineates the MUC1-expressing tumor, with the tumoral activity concentrations growing over the course of the 120 h experiment (top)." (PMID 32429033, 2020). "Tecemotide, also known as L-BLP25 or Stimuvax, is designed to elicit an antigen-specific cellular immune response against MUC1, which is one of the first TAAs identified by human tumor-specific T-cells." (PMID 32807223, 2020). "MUC1 oncoprotein is aberrantly expressed at high levels in most human neoplasms, and MUC1 plays important roles in development and progression of malignant tumors." (PMID 32993581, 2020). "CAR-T cells specific to MUC1 can effectively destroy GC tumor cells, but more research is needed to improve the safety of this therapy." (PMID 32560392, 2020). "Our data showed that MUC1 overexpression significantly mitigated the effects of disulfiram on tumor cells, presented by stronger capability in proliferation, migration, and less apoptosis." (PMID 33375426, 2020). "ANX A2 expression is immunohistochemically examined, as well as both epithelial membrane antigen (EMA) and mucin-1 glycoprotein (MUC-1), the gold-standard markers for luminal differentiation, in the background tumor components of a case of IMPC." (PMID 32695546, 2020). "They found that “dual-targeted” T cells kill ErbB2+ tumor cells efficiently, but their proliferation requires coincubation with the target cells with both Tn-MUC1 and ErbB2 expression." (PMID 32194541, 2020). "Overall, these results indicate that the expression level of MUC1 is detrimental to determining the anti-tumor activity of disulfiram." (PMID 33375426, 2020). "The tracer showed fast clearance via the kidneys, while still providing tumor-to-background ratios of 4.0 ± 0.2 in low MUC1-expressing HepG2 tumor cells." (PMID 33371487, 2020). "In tumor tissues, TF is expressed on many glycoproteins, such as mucin Muc1, CD44v6, CD133, and integrins." (PMID 32280709, 2020). "We have recently shown that an anti-MUC1 antibody can be used as a therapeutic antibody when conjugated to the immune modulating agent CpG ODN via enhanced NK cell anti-tumor activity against PDA tumors." (PMID 31114758, 2019). "Overexpression of MUC-1 has been observed to play a role in tumor progression, invasion, metastasis and therapy resistance." (PMID 30987642, 2019). "Previously, we have shown specific localization of TAB004 in breast and pancreatic tumors in human MUC1 transgenic mouse models in which the entire glandular epithelia express normal human MUC1, further validating the tumor-specificity of TAB004." (PMID 31514488, 2019).